MTOR (mechanistic target of rapamycin kinase)
Diseases named in the same sentence as MTOR in open-access papers (continued):
Sharing a sentence is not in itself a finding about the gene and the disease.
cancer (continued). "PI3K/Akt/mTOR signaling pathway is potential targets for HER2 + cancer with drug resistance considering the anticipated synergy effect." (PMID 36457011, 2022). "In general, it appears that mTOR inhibitors have mixed efficacy in patients across tumor indications and among patients with the same type of cancer." (PMID 36221123, 2022). "In cancers, a small number of studies have demonstrated a positive correlation between PIK3CA mutational status and upstream activation of the mTOR pathway." (PMID 35094709, 2022). "Aberrant activation of the PI3K/Akt/mTOR pathway had been found in various cancers and had been suggested to stimulate proliferation and drug resistance." (PMID 35433438, 2022). "Compared to single agent neratinib, combining it with everolimus (an mTOR inhibitor) significantly inhibited cancer growth with marked suppression of Ki67 and enhancement of apoptosis." (PMID 36387174, 2022). "Our results indicated that the target genes of hub miRNAs for upregulated expression enriched metabolic pathways, mTOR signaling pathway, and proteoglycans in cancer." (PMID 35406675, 2022). "TRPV4 are activated under low mechanical confinement along with Akt/mTOR activation and drive cytoplasmic localization of p27Kip1, thus facilitating entry to the S phase and proliferation in cancer cells." (PMID 35163745, 2022). "The PI3K/AKT/mTOR axis is an important intracellular signaling pathway that regulates the progression of various cancers." (PMID 35402614, 2022). "Various signaling pathways participate in the evodiamine-induced cancer cell apoptosis such as mTOR signaling, STAT3 signaling, and Bax/Bcl-2." (PMID 35899176, 2022). "Intriguingly, elevated nuclear mTOR expression was observed in African American PCa and other advanced cancers." (PMID 36077039, 2022). "According to previous reports, eIFs, particularly some eIFs, with their main regulator mTOR, seem to play a crucial role in the development of various cancer entities, such as HCC." (PMID 35159342, 2022). "Akt inhibitors increase the sensitivity of cancer cells to chemotherapy and radiotherapy, and inhibitors of PI3K and mTOR play an important role in the treatment and drug resistance of cancer." (PMID 34981275, 2022). "mTOR is the central hub that also mediates dynamic signaling crosstalk and metabolic flux between cancer cells and cells from the tumor microenvironment." (PMID 35163745, 2022). "Apart from those, numerous cancer malignant phenotypes-associated pathways, including PI3K/AKT/mTOR, TGF-β signaling and wnt/β/cantenin pathways, were more prevalent in the high-risk group." (PMID 36685508, 2022). "Myc-regulated protein synthesis is modulated by the mTOR-dependent phosphorylation of eukaryotic translation initiation factor 4E binding protein-1 (4EBP1), which is required for cancer cell survival in Myc-dependent tumours." (PMID 36289203, 2022). "A number of anticancer agents, including mTOR inhibitors, can induce oxidative injury and ROS production to exacerbate cancer cell death." (PMID 35717530, 2022). "It should be noted that while many oncogene-addicted cancers, including mTOR, show striking initial responses to acute targeted therapies, most patients ultimately develop resistance being targeted 47-49." (PMID 36438486, 2022). "MYC, CCNE1, TERT, KRAS and genes from the PI3K/AKT/mTOR pathway (e.g. PIK3CA) are amongst the commonest amplified cancer genes in HGSOC2,9–13." (PMID 36289203, 2022). "PI3K/AKT/mTOR pathway is among the commonly dysregulated pathway and is actively involved in the regulation of cancer cell survival, proliferation, growth and metabolism." (PMID 36618350, 2022). "Deregulation of mTOR signaling occurs in many diseases, including cancer, diabetes, autoimmunity, and neurological disorders." (PMID 36041631, 2022). "On the other hand, LAT1 provides cancer cells with the essential amino acid not only for protein synthesis but also for stimulating cell growth via mTOR." (PMID 36536190, 2022).
cancer (continued). "TBK1 knockdown induces the activation of mTOR-p70S6K signaling and increases the sensitivity of cancer cells in bone marrow niches to docetaxel treatment as demonstrated by a xenograft model." (PMID 35395857, 2022). "Temsirolimus, as a selective mTOR inhibitor, is used to effectively suppress the growth of cancer cells." (PMID 36104717, 2022). "It has recently been shown that mTOR is able to mediate anti-cancer drug resistance by suppressing autophagy." (PMID 36555736, 2022). "In conclusion, this work clearly demonstrates the therapeutic potential of ATP-binding mTOR inhibitors not only in cancer research, but also in longevity studies." (PMID 36561137, 2022). "The mechanistic (formally “mammalian”) target of rapamycin (mTOR) pathway serves as a crucial regulator of various biological processes such as cell growth and cancer progression." (PMID 36085200, 2022). "PI3K/AKT/mTOR pathway activation has been observed in various cancers because of its capacity to inhibit apoptosis and promote cellular proliferation." (PMID 35592520, 2022). "Abnormal PI3K/AKT/mTOR pathway are very common in human cancers and the activation or imbalance of this signaling pathway often favors tumor cells survival." (PMID 35458629, 2022). "The influence of translational signatures on differentiation programs is therapeutically interesting, as not only mTOR inhibitors, but also cytotoxic drugs, induce cancer cell plasticity by enhancing translation of NODAL, NANOG, and SNAIL mRNA isoforms." (PMID 35814409, 2022). "Ceramides are tumor suppressors involved in immunomodulation and can inhibit cancer cell proliferation by blocking the cell cycle, or by triggering the autophagic response of cancer cells by downregulating mTOR activity." (PMID 35457057, 2022). "Given the role of mTOR in cancer and its physical interaction with the lysosome and NPC1, the western blot was used to evaluate how NPC1 silencing affects mTOR signaling." (PMID 35884604, 2022). "The PI3K/Akt/mTOR signalling pathway controls many key biological functions of cells, such as proliferation, migration, and growth, which are hallmarks of cancer." (PMID 36012280, 2022). "Lately, OLA has been identified as a metabolo-epigenetic inhibitor of the mammalian target of rapamycin (mTOR) kinase and DNA methyltransferases (DNMTs) in cancer stem cells." (PMID 36355509, 2022). "Less common alterations in AKT, TSC1, TSC2, LKB1, mTOR and other critical genes have also been found in cancer." (PMID 35328644, 2022). "Results show for the first time that NB exerts an anti-cancer activity through the direct interaction to Akt and mTOR proteins." (PMID 36180880, 2022). "We used inducible, muscle‐specific Raptor ko (mTORC1) mice to determine the effect of reduced mTOR signalling during cancer cachexia." (PMID 34741441, 2022). "In most cancers, it interferes with protein targets of the phosphatidylinositol 3 kinase/protein kinase B/mechanistic target of rapamycin (PI3K/Akt/mTOR) and mitogen-activated protein kinase (MAPK) signaling pathways." (PMID 36077275, 2022). "DHW-208, a pan PI3K inhibitor, is a novel 4-amino-quinazoline derivative containing hydrophilic groups and suppressed the growth of cancer cells by inhibiting the PI3K/AKT/mTOR-signaling pathway." (PMID 35903690, 2022). "The PI3K/AKT/mTOR signaling pathway is a well-known signaling pathway in cancer formation and metastatic spread." (PMID 35682652, 2022). "The interactions of LNEO with DNA and the PI3K/mTOR dual inhibitor indicate that LNEO-loaded PLGA NPs have the potential to be used in cancer therapy as a novel phytotherapeutic agent-based controlled-release system." (PMID 35335262, 2022). "The mechanistic target of rapamycin (mTOR) is an evolutionary conserved serine-threonine kinase present in multiple cancers." (PMID 36185289, 2022). "These compounds act on the anabolic mTOR axis of the cancer cell, suppressing protein synthesis and rescuing the endogenous inhibitor DEPTOR." (PMID 36388131, 2022).
cancer (continued). "LKB1-deficient cancer cells contain an overactive AMPK “energy sensor,” which inhibits cellular death and promotes glucose, lipid, and protein synthesis via the mTOR protein complex." (PMID 35165542, 2022). "In light of the previous discussion, this article reviews the current knowledge on the mTOR signaling pathway by highlighting its structure, various functions, and the upstream and downstream signaling related to cancer." (PMID 36428613, 2022). "Rapamycin and its analogs (rapalogs, including everolimus, temsirolimus, and ridaforolimus) are FDA approved as mTOR inhibitors for the treatment of human diseases, including cancer and autoimmunity." (PMID 36264642, 2022). "The mTOR pathway is abnormally activated in many cancers, regulating the metabolism and the progression of cancer cells." (PMID 36059961, 2022). "Previous studies showed that metformin triggers autophagy by AMPK activation, which leads to subsequent inhibition of mTOR signaling, as well as promoting apoptosis in cancer cells." (PMID 35267590, 2022). "The mammalian target of rapamycin (mTOR) is a key modulator of signals governing protein and lipid biosynthesis and cell-cycle progression, so mTOR can drive cancer growth by activating the lipid and protein biosynthesis." (PMID 35402243, 2022). "The PI3K/Akt/mTOR signaling has been found to be frequently dysregulated pathways of cancer cell proliferation and survival." (PMID 36234977, 2022). "Preclinical studies have demonstrated several anti-cancer molecular mechanisms of metformin including mTOR inhibition, cytotoxic effects and immunomodulation." (PMID 36497414, 2022). "The reason anti-cancer effects are more effective in immunocompetent mice is that TEM suppresses cancer cell proliferation by inhibiting mTOR levels and promoting immune cell-mediated anti-cancer effects." (PMID 36077620, 2022). "HIF1α, as well as phosphoinositide 3-kinase/protein kinase B/mammalian target of rapamycin (PI3K/Akt/mTOR) pathways are crucial regulators of cancer cell proliferation and glycolytic metabolism." (PMID 35163570, 2022). "mTORC1 serves as a downstream effector for several commonly disrupted oncogenic pathways, including the PI3K/AKT and MAPK pathways, and the mTOR pathway is overactive in various tumor types, making mTOR a target for cancer treatment." (PMID 35402264, 2022). "Natural products have been an incomparable source of anticancer drugs and have potentially affected the modulation of autophagy by downregulation of the PI3K/Akt/mTOR pathway in different cancer cells." (PMID 36428613, 2022). "We used GSEA to investigate the possible signaling pathways and cancer correlated with expression of mTOR." (PMID 35082928, 2022). "This pathway is activated by Wnt/GSK-3β independently of β-catenin and is considered another anti-oncogenic effect of GSK-3β in PDAC as mTOR is a major pro-cancer effector in PDAC." (PMID 36430630, 2022). "High ZC3H13 expression was associated with low expression of the RIBOSOME, positive correlation of the MAPK signaling pathway, pathways in cancer and mTOR signaling pathway, NOTCH signaling pathway." (PMID 36712973, 2022). "Our dissection of the molecular mechanisms underpinning GOLPH3 interactions with the mTOR pathway now sets the stage to understand the notable effects of GOLPH3 overexpression on mTOR signaling and autophagy observed in a broad set of cancer contexts." (PMID 36435842, 2022).
cancer (continued). "The Transwell-based assay showed that the migration and invasion capabilities of cancer cells were increased by activating mTOR." (PMID 35449152, 2022). "Future studies will be needed to determine the pathological relevance of isoform switching by mTOR signaling in cancer and other diseases." (PMID 36293270, 2022). "The epidermal growth factor receptor (EGFR)/AKT/mechanistic target of rapamycin (mTOR) signaling pathway is one of the most important pathways, which is considered as a master regulator for cancer." (PMID 36032960, 2022). "The cell cycle, mTOR signaling pathway, NOTCH signaling pathway, endocytosis, and pathways in cancer were enriched in the high-risk group." (PMID 36304466, 2022). "According to mTOR-centric hyperfunction theory, aging is the sum of age-related diseases, such as osteoporosis, Alzheimer’s disease, diabetes mellitus, cancer, etc.." (PMID 36561137, 2022). "Dysregulated mTOR activation is a frequent observation in cancer and represents a process in cancerogenesis." (PMID 35402264, 2022). "The PI3K-Akt-mTOR signalling pathway is among the most common intracellular signalling pathways that are often abnormally activated in many human cancers and participate in different biological effects, such as cell cycle progression and cell proliferation." (PMID 35614940, 2022). "Several cancers have demonstrated abnormal PI3Kα/Akt/mTOR signaling pathway activation, in which PIK3CA gene expression has been implicated." (PMID 36145724, 2022). "Of note, in these experimental settings, NAMPT and mTOR inhibition synergized in inducing cytotoxicity in cancer cells." (PMID 36077374, 2022). "As a corollary, mTOR inhibitors promote the growth of cells that rely on extracellular proteins as an obligatory nutrient source, such as cancer cells that reside in nutrient-poor tumour microenvironments." (PMID 35977928, 2022). "The PI3K/Akt/mTOR pathway is a key intracellular signal transduction pathway that has provoked great interest as a therapeutic target in cancer." (PMID 36046843, 2022). "Top 100 differentially expressed lncRNAs were associated with pathways activated in cancer, including EGF receptor, Wnt, and mTOR signaling pathways." (PMID 36359790, 2022). "Bypassing pathways and feedback mechanisms leading to resistance are a major concern of mTOR inhibitors in cancer." (PMID 35216092, 2022). "On the other hand, Bcl-2, NF-κB, and Akt-mTOR are antiapoptotic factors, which are down-regulated in a combination treatment of HT and anti-cancer drugs or natural products." (PMID 35453310, 2022). "By the way, AMP-activated protein kinase (AMPK) has been reported to be involved in regulating the interaction between PI3K/AKT/mTOR pathway 61 and PD-1/PD-L1 because of aberrant energy status in cancer." (PMID 36313041, 2022). "The main autophagy regulator, mTOR, was found to be reduced in patients with a cancer spreading and in HER2 positive tumors." (PMID 35877414, 2022). "Several PI3K/Akt/mTOR pathway inhibitors have been investigated to be effective against a variety of cancers, and sufficient clinical data have been obtained." (PMID 35392233, 2022). "The aberrant expression of ZEB1 has been reported in a variety of human cancers, where it is generally believed to foster migration, invasion, and metastasis via mTOR signaling." (PMID 36077992, 2022). "HIF-1 also increases oncogene activity through the inactivation of tumor suppressors (e.g., VHL) and through PI3K/AKT/mTOR in cancer cells, ultimately driving cancer progression and metabolic alterations that are resistant to treatment." (PMID 36778600, 2022). "Cancer cells express glycolysis-related enzymes, which are regulated by the mTOR pathway, affecting the progression of tumors." (PMID 36059961, 2022).
cancer (continued). "In the cancer context, mTOR activation is a critical regulators to enhance the proliferation and colony formation capability of several CSC types, including breast." (PMID 35208277, 2022). "Rapamycin inhibits mTORC1 by binding to the FRB domain of mTOR and hence its use in cancer treatment." (PMID 35225948, 2022). "The aberrant activation of PI3K/Akt/mTOR signaling is one of the most frequent events in human cancer, especially in RCC and serves to disconnect the control of cell growth, survival and metabolism from exogenous growth stimuli." (PMID 36203437, 2022). "Glutamine metabolism was shown to inhibit autophagy in cancer cells through the activation of the mTOR pathway." (PMID 36497226, 2022). "The current review summarizes the use of sirolimus and its derivatives and addresses potential limitations in targeting mTOR signaling for the treatment of cancer." (PMID 36109789, 2022). "On the other hand, activation of AKT/mTOR is known to promote tumor growth and metastasis with many mechanisms underlying the development of the disease and the resistance to AKT/mTOR inhibitors in cancer cells." (PMID 35053341, 2022). "Functional assays revealed that ATRAP participates in promoting cell growth, metastasis, and aerobic glycolysis, while microarray analysis showed that ATRAP can activate the AKT/mTOR signaling pathway in cancer progression." (PMID 35414770, 2022). "The expression of components of several cancer-related signaling pathways, such as Mammalian Target of Rapamycin (MTOR), PI3K/AKT, Insulin-like Growth Factor-1 (IGF-1) and Epidermal Growth Factor Receptor (EGFR) pathways are frequently disturbed in LUAD." (PMID 36446361, 2022). "Sophocarpine inhibited the progression of CRPC by downregulating the PI3K/AKT/mTOR signaling pathway and showed a potential to be an anti-cancer agent against CRPC." (PMID 36132221, 2022). "The activation and inhibition of the PI3K/AKT and mTOR pathways in human cancer cells determine the survival, carcinogenicity, metastasis, and invasion of cancer cells." (PMID 36142874, 2022). "mTOR is frequently dysregulated in various human cancers and plays a crucial role in multiple biological processes, including stemness and chemosensitivity regulation." (PMID 36056355, 2022). "Strophanthidin, a natural cardiac glycoside, causes apoptosis and DNA damage in several cancer cells (breast, lung, and liver), associated with down-regulating PI3K/AKT/mTOR." (PMID 36139919, 2022). "A careful examination of some cell functions influenced by mTOR-targeting UCA1 is warranted to provide more evidence for their impacts on cancer cells in the future." (PMID 36230902, 2022). "NF-ƙB, EGFR, PTEN/PI3K/AKT, Wnt, HIF-1α, STAT3 and AKT/ERK/mTOR signaling pathways are among those being influenced by dysregulation of miR-671 in different cancers." (PMID 36545507, 2022). "mTOR inhibitors that promote cancer cell death and boost effector functions in T cells can be combined to improve ICI therapeutic outcomes." (PMID 35883111, 2022). "Targeting of mTOR is attractive, indeed, some of the mTOR inhibitors have been development to treat cancer, including rapamycin analogs (rapalogs), everolimus and temsirolimus." (PMID 35437691, 2022). "The PI3K/AKT/mTOR pathway is one of the major signaling pathways that has been shown to be important in cancer and is involved in a variety of cell functions, including proliferation, growth, glucose metabolism, differentiation and EMT." (PMID 35277194, 2022). "For instance, the highest mTOR intensities were detected in grade 3 cancers, while moderate and low mTOR intensities were detected in grade 2 and 1 patient specimens, respectively." (PMID 36077039, 2022). "To date, first and second generations of mTOR inhibitors have been introduced for the treatment of cancer." (PMID 36293326, 2022). "The PKA can interact with downstream IRS-1 to activate the PI3K/AKT/mTOR pathway related to cancer cell survival, proliferation, and growth." (PMID 35798765, 2022).